KEAP1 (kelch like ECH associated protein 1)
Diseases named in the same sentence as KEAP1 in open-access papers (continued):
Sharing a sentence is not in itself a finding about the gene and the disease.
cancer (continued). "Thus, we successfully generated 3LL cancer cell lines with marked NRF2 activation by means of CRISPR-Cas9-mediated mutations of the Keap1 gene." (PMID 41035689, 2025). "However, in cancer cells, mutations in KEAP1 or NRF2 hyperactivate NRF2, protecting them from oxidative stress and therapy-induced damage." (PMID 39935430, 2025). "The Nrf2/Keap1 pathway has extensive interactions with mitochondria, and in cancer cells, glycolysis/OXPHOS is closely linked to Bach1, in addition to Nrf2 and p21, and Keap1 is closely linked to mitochondrial biogenesis/mitophagy in metastatic CRC tumors, attempting to identify new drug targets." (PMID 41304943, 2025). "Nrf2 (Nuclear factor erythroid 2-related factor 2) is a transcription factor implied in the activation of genes involved in protection against oxidative stress in cancer cells and its degradation is triggered by interaction with Keap1 (Kelch-like ECH-associated protein 1)." (PMID 38339078, 2024). "In summary, the diminished expression and functional loss of Keap1 may result in the sustained activation of Nrf2, thereby providing growth support for cancer cells." (PMID 39664581, 2024). "While the functional impact for these mutations is generally known for NRF2 and KEAP1, the biological relevance in cancer for most of the missense mutations for the SWI/SNF subunits remains unknown." (PMID 38358974, 2024). "Interestingly, multiple mechanisms, e.g., mutations in the Nrf2/Keap1 pathway, cause Nrf2 dysregulation in many cancer types." (PMID 39456749, 2024). "Together these data suggest that KEAP1 could be pursued as a means to selectively kill certain types of ARID1A-deficient cancer." (PMID 39272807, 2024). "Mutations in NRF2 and KEAP1 have been identified in multiple cancers with varying prevalence." (PMID 38424190, 2024). "However, in cancer cells with mutated KEAP1, this regulatory mechanism is disrupted, resulting in the accumulation of NRF2." (PMID 39596025, 2024). "Consequently, strategies such as inhibiting PI3K and NRF2 or activating GSK-3β, along with NRF2 repressor Kelch-like ECH-associated protein 1 (KEAP1), hold promising therapeutic potential against cancer." (PMID 38255314, 2024). "Besides, KEAP1 promoter methylation has been linked to poor prognosis in multiple cancers, including NSCLC, breast cancer, and malignant gliomas." (PMID 38521813, 2024). "Furthermore, KEAP1 mutations have been associated with radioresistance in multiple cancer types, including prostate cancer, head and neck squamous cell carcinoma, and meningioma." (PMID 39695143, 2024). "Further investigation of a NRF2/COX-2/PGE2 axis may yield justification for combination immunotherapy treatments using COX-2 inhibitors to “sensitize” immune cells and checkpoint blockade to induce anti-cancer responses in patients bearing KEAP1 mutations." (PMID 38542481, 2024). "Activated NRF2 by KEAP1 is associated with an increased progression of cancer and reduced survival." (PMID 39000120, 2024). "Given that KEAP1 mutations are associated with poor response to immune checkpoint inhibitors, it can be envisioned that in KEAP1 mutant cancers with enhanced NFκB signaling such approaches could be successful." (PMID 38184997, 2024). "Mutations in Nrf2 and Keap1 and their pathways lead to cancer events." (PMID 37841775, 2023). "Notably, cell lines harboring KEAP1 mutations were generally resistant to FINs in other cancer types." (PMID 37633973, 2023). "The Keap1/Nrf2-ARE (Kelch-like ECH-associating protein 1) antioxidant stress signaling pathway plays a crucial role in a variety of oxidative stress-related diseases including cancer." (PMID 37175549, 2023). "Missense mutations in Nrf2 or mutations of KEAP1, blocks the KEAP1 and Nrf2 interaction and consequently, Nrf2 concentration increases and translocates to the nucleous and activates an antioxidant response system which reduces cancer cells death." (PMID 37712005, 2023).
cancer (continued). "However, persistent NRF2 activation in established cancer cells, often resulting from mutations in KEAP1 or NRF2, promotes tumor cell survival, growth, and resistance to therapy." (PMID 38060331, 2023). "Similarly, mutations within the Keap1-binding domain of Nrf2 impair Keap1 recognition, allowing Nrf2 to escape Keap1-mediated degradation and accumulate at high levels in cancer cells." (PMID 36552553, 2022). "Keap1 mutations and the resulting Nrf2 activations have been reported in many cancers." (PMID 35945195, 2022). "Since gain-of-function mutations in genes that encode for the Nrf2 pathway are found in various cancers, we hypothesized that constitutive activation of Nrf2 by hepatic Keap1 deletion spontaneously induces liver carcinogenesis." (PMID 36209041, 2022). "Some functional Keap1 mutations have been detected in various cancers and may lead to increased Nrf2/ARE gene transcription expression." (PMID 34861061, 2022). "Keap1 mutations regulate Nrf2 activity and lead to chemoresistance in cancers." (PMID 35945195, 2022). "Besides, gain-of-function mutations of Nrf2 and loss-of-function mutations of Keap1 cause several cancers and provoke drug and radiation resistance." (PMID 35906617, 2022). "The Keap1 mutation has a role in the development and progression of various human cancers." (PMID 34861061, 2022). "Mutations in KEAP1 are associated with a worse prognosis in cancer." (PMID 36741696, 2022). "Moreover, mutations in Keap1 are associated with Nrf2 constitutive activation in cancer cells and radioresistance." (PMID 36230484, 2022). "Besides the Keap1 mutations, gain of function mutations of Nrf2 have also been identified in human cancers for example esophageal carcinoma, lung, head and neck cancer." (PMID 35773670, 2022). "In order to elucidate whether mutations found in the cBioPortal cancer genomics database affect the binding of DPP III to KEAP1 we combined several experimental and computational approaches." (PMID 35216111, 2022). "Several upcoming clinical trials are designed to explore the therapeutic benefit of compounds that inhibit NRF2 in advanced cancer patients harboring mutations in NFE2L2 or KEAP1 (ClinicalTrials.gov, NCT02417701; ClinicalTrials.gov, NCT04267913; ClinicalTrials.gov, NCT03872427)." (PMID 33769711, 2021). "Therefore, WDR23 plays a major role in the regulation of Nrf2 in cancer cells bearing Keap1 mutation." (PMID 33895141, 2021). "Deregulation of the Nrf2 pathway and mutations in Keap1 has been associated with various cancer." (PMID 33922139, 2021). "However, as one of the main factors regulating oxidative stress in the body, various recent studies have shown that Keap1 mutations are associated with cancers." (PMID 34466284, 2021). "In line with this, it was shown that cancer cells with KEAP1 mutation and/or NRF2 hyperactivation exhibit increased glutamine dependency and enhanced sensitivity to glutamine deprivation or glutaminase inhibition, partly via high SLC7A11-mediated glutamate export in these cancer cells." (PMID 33000412, 2021). "In addition to disruption of the regulation by Keap1, Nrf2 has also been associated with carcinogenesis by interacting with proteins implicated in cancer." (PMID 34202320, 2021). "Additionally, mutations in KEAP1 were also detected in liver and gallbladder, which caused over expression of antioxidant and phase II detoxification enzymes that have roles in cancer chemo-resistance." (PMID 33808001, 2021). "This notion raised the relevant question of whether activation of the Keap1/Nrf2 pathway was an early event, possibly driving cancer development, or a change linked to the neoplastic transformation typical of late stages of cancer progression." (PMID 33053665, 2020).
cancer (continued). "In this context, the authors proposed that the use of glutaminase inhibitors alone or in combination with NRF2 inducers might be a valid therapeutic strategy to target different cancers respectively carrying functional or mutated forms of the KEAP1 gene." (PMID 32443774, 2020). "Importantly, it has been proposed that the co-occurrence of KEAP1 mutations with pre-existing oncogenic alterations can induce metabolic addicted phenotypes in cancer cells." (PMID 32443774, 2020). "As an example, in later stages of cancer, Nrf2 and Keap1 are mutated and Nrf2 activity increased." (PMID 32425794, 2020). "Somatic mutations in KEAP1 lead to activation of the NRF2 signaling pathway in various cancers." (PMID 32327612, 2020). "Notably, many studies have revealed that the loss of interaction between NRF2 and KEAP1 causes tumor development in multiple cancer types." (PMID 32751080, 2020). "Interestingly, the mutational frequency in NFE2L2 and KEAP1, 3% and 5% respectively, is much lower than in some other cancer types." (PMID 33276631, 2020). "Moreover, our results indicate that a subset of cancer‐associated KEAP1 mutations abrogate this function." (PMID 33173725, 2020). "Autophagy may also protect against cancer via suppression of oxidative stress via modulation of nuclear factor erythroid 2-related factor 2 (Nfe2l2/Nrf2)/kelch-like ECH-associated protein 1 (Keap1) and SQSTM1/p62 pathway." (PMID 33224954, 2020). "Together, a tightly regulated balance of NRF2 and KEAP1 interaction is essential to protect cells or tissues from oxidative stress, and the failure of that mechanism (e.g., mutations of critical amino acids) triggers cancer development." (PMID 32751080, 2020). "However, little is known about how the binding patterns of NRF2 differ between normal and cancer cells, specifically in KEAP1-mutated A549 (NSCLC) cells." (PMID 31884422, 2019). "Lastly, we hypothesized that tumor genetics would also alter TIF composition, and studied the effect of Keap1 loss because Keap1 null cancer cells have dramatic alterations in cell-intrinsic metabolism." (PMID 30990168, 2019). "Somatic mutations in NRF2 (gain of function mutations) and KEAP1 (loss of function mutations) result in constitutive activation of Nrf2 and its target genes, and these mutations have been identified in many different cancers." (PMID 31022969, 2019). "Loss-of-function mutations in Keap1 have been identified in several human cancers." (PMID 30811526, 2019). "A lncRNA, KRAL (Keap1 regulation-associated lncRNA) directly interacts with miR-141as a competing endogenous RNA (ceRNA) and increases the expression of Keap1, leading to the inactivation of Nrf2 and the enhancement of chemosensitization to cancer cells." (PMID 31511020, 2019). "Besides somatic mutations of KEAP1, epigenetic alterations in promoter regions of the KEAP1 gene can lead to aberrant activation and nuclear accumulation of Nrf2 protein in cancer cells." (PMID 31022969, 2019). "It is now well known that loss-of-function mutations of the KEAP1 gene or gain-of-function mutations in NFE2L2 enhance the resistance of cancer cells to anticancer drugs, such as etoposide and carboplatin, and it is associated with poor outcome of platinum-based advanced NSCLC patients." (PMID 29643973, 2018). "Despite the powerful effects exerted by these somatic mutations in Keap1 or Nrf2 that lead to the constitutive activation of Nrf2, such mutations were only found in ~1.45% of all cancer samples examined in studies published in COSMIC 2018 (COSMIC; http:// cancer.sanger.ac.uk/cosmic)." (PMID 29973599, 2018). "In addition, it is important to note that amino acid mutations of Keap1 were found to highly expressed in the human lung, breast and other somatic cancers, and these mutants were also identified leading to the deteriorative activation of Nrf2." (PMID 30042301, 2018). "There have been reports about somatic mutations of Keap-1 and Nrf2 in many human cancers." (PMID 29716554, 2018).
cancer (continued). "Somatic mutations of Nrf2 and Keap1 have also been found in cancers at high frequency; these mutations could cause persistent activation of Nrf2 via disrupting the interaction between Nrf2 and Keap1." (PMID 29930914, 2018). "Furthermore, somatic mutations of Keap1, a characteristic of certain cancer phenotypes, result in constitutive Nrf2 activation, as does the silencing of Keap1 expression by miRNAs, or by epigenetic hyper-methylation of the Keap1 promoter." (PMID 30071261, 2018). "The CRL3-KEAP1-NRF2 pathway contributions to cancer development are reinforced by the observed deregulation of KEAP1 and the presence of CUL3 mutations that could lead to NRF2 overexpression in many cancers (Chen and Chen, 2016 and references therein)." (PMID 29594129, 2018). "In light of the impact WDR23 had on the NRF2 activity in untransformed cells, we predicted that WDR23 could compensate for KEAP1 loss in cancer cell lines derived from human tumors." (PMID 28453520, 2017). "For each cancer type, mutations in KEAP1 predicted sensitivity to CB-839." (PMID 28967864, 2017). "KEAP1 mutations predict sensitivity to glutaminase inhibitors across multiple cancer subtypes." (PMID 28967864, 2017). "In addition, they demonstrated that this molecule, in combination with platinum-based cancer drugs, increases the drug-induced cytotoxicity in Keap1-deficient NSCLC tumors compared to single agent treatment." (PMID 29261130, 2017). "These mutations lead to activation of the Keap1‐Nrf2 pathway that may protect not only normal cells but also cancer cells from the toxicity of reactive oxygen species." (PMID 27650414, 2016). "Importantly, NRF2 activation and KEAP1 inactivation mutations leading to permanent constitutive adaptive activation of the NRF2 pathway are frequently observed in cancers." (PMID 26770651, 2016). "In the analysis of clinical samples, it was found that gain-of-function mutations in NRF2 exist in carcinomas of esophagus, skin, and larynx, while loss-of-function mutations in KEAP1 are observed in carcinomas of lung, gall bladder, ovary, breast, liver, and stomach." (PMID 27340506, 2016). "Accumulating evidence suggests that KEAP1 loss or mutation—which results in high levels of sustained NRF2 activity—may promote cancer growth and increase chemoresistance." (PMID 26301506, 2015). "These mutations destabilize the Keap1–Nrf2 interaction leading to Nrf2 protein stabilization and induced transcriptional responses that protect cancer cells from environmental stresses, including the potential toxicity of cancer drugs or radiation therapy." (PMID 26057936, 2015). "We talk about common pathways through which cancer progresses (such as nuclear factor erythroid 2-related factor 2-Kelch-like ECH-associated protein 1 (Nrf2-Keap1), sirtuin-forkhead box O (SIRT-FOXO) and others), analyzing how diverse molecules associated with these pathways conform to hormesis." (PMID 26694419, 2015). "But in many cancer cells, loss of Keap1 function activates Nrf2 and promotes cancer growth." (PMID 26273424, 2015). "In addition to genetic variations, multiple somatic mutations identified in the KEAP1 recognition domain of NRF2 in cancer cells have been found to be oncogenic due to dysregulation of NRF2 homeostasis by its excess “gain of function”." (PMID 23936606, 2013). "However, somatic mutations in Keap1 and Nrf2 that interrupt Keap1-Nrf2 association and lead to constitutive Nrf2 activation are frequently detected in human cancers." (PMID 23819012, 2013). "Thus, studies on the deregulation of the KEAP1/NRF2 pathway have enhanced our understanding of the molecular mechanisms associated with cancer." (PMID 24137397, 2013). "Mutations that result in KEAP1 loss of function are thought to facilitate cancer cell expansion." (PMID 23676014, 2013).
cancer (continued). "Impaired Keap1 activity and somatic mutation of Nrf2 lead to full Nrf2 activation, and cancer cells may acquire a protective mechanism against the surrounding microenvironment, resulting in cancer cell proliferation, differentiation, and chemoresistance." (PMID 22325485, 2012). "Thus, the heterozygous KEAP1 mutation conferring the growth advantage on cancers is consistent with the two-site binding model and hinge and latch model of the Keap1–Nrf2 system." (PMID 23272301, 2012). "Evidence is now accumulating for the frequent mutation of either Keap1 or Nrf2 in human cancers." (PMID 24212776, 2011). "In this section we have described how mutations in both Keap1 and Nrf2 provide malignant cells with the capacity to protect themselves from harmful or apoptotic effects, thus representing a key survival factor in different types of cancer." (PMID 24212776, 2011). "Indeed, recent pan‐cancer integrated genomic and functional studies demonstrate that KEAP1 variants of unknown significance (VUS) can phenocopy established oncogenic KEAP1 mutations." (PMID 40600748, 2025). "In addition, lower-level infiltrations of other types of immune cells are often observed in patients with KEAP1-mutated LUAD in the Cancer Genome Atlas (TCGA) database, the Tumor Immune Estimation Resource (TIMER) database, and the randomized phase III IMpower131 study." (PMID 41035689, 2025). "Cancer-derived KEAP1 mutations have also been reported to influence or promote the formation of p62 bodies, though the extent to which p62 phosphorylation, KEAP1 sequestration, and/or autophagy suppression contribute to the underlying pathogenesis needs further investigation." (PMID 40437287, 2025). "To gain a more comprehensive view about intrinsic pathway changes within KEAP1 mutated cancer cells, we performed differential gene expression analysis with pseudo bulk gene expression profile of aggregated cancer cells and followed by GSEA analysis using the Maynard dataset." (PMID 38241355, 2024). "The so-called “double-edged sword” of up-regulating the kelch-like ECH-associated protein 1 (Keap1) and nuclear factor erythroid 2-related factor 2 (Nrf2) pathway must, however, be considered when applied to patients with tumors or other actively growing cancers." (PMID 39770075, 2024). "Notably, many cancer cells exhibit elevated endogenous antioxidant defences due to the inherent overexpression of nuclear factor erythroid 2-related factor 2 (Nrf2), which is linked to the disruption of Keap1." (PMID 38794239, 2024). "Interestingly, cancers with mutations in Kelch-like ECH-associated protein 1 (KEAP1), the negative regulator of the nuclear factor erythroid 2-related factor 2 (NRF2) transcription factor, are resistant to immune checkpoint inhibition and correlate with decreased lymphoid cell infiltration." (PMID 38542481, 2024). "The well-established NFE2L2/KEAP1 system has emerged as the cellular stress-sensitive master transcriptional regulator of various downstream targets, predominantly genes encoding anti-oxidative and detoxification pathways, associated with both cancer and cardiovascular susceptibility in humans." (PMID 37627583, 2023). "Furthermore, whereas transient Nrf2 activity protects against cancer, constitutive Nrf2 activation caused by Keap1 or Nrf2 genetic variations may promote cancer progression and tumor growth." (PMID 36747120, 2023). "In addition, the association between NRF2/KEAP1 signaling and cancer aggressiveness is certain." (PMID 35754474, 2022). "Notably, KEAP1 missense or nonsense mutations were reported in endometrial carcinomas, as well as gall bladder, breast, cervical, and ovarian cancers." (PMID 34371961, 2021). "Furthermore, low expression of YTHDF1 can reduce the sensitivity of cancer tissue to cisplatin was attributed to the Keap1-Nrf2-AKR1C1 axis (Kelch-like ECH-associated protein 1, NF-E2 p45-related factor 2 and antioxidant genes including aldo-keto reductases 1C1)." (PMID 33692959, 2021).